ADIPOQ (adiponectin, C1Q and collagen domain containing)
Diseases named in the same sentence as ADIPOQ in open-access papers (continued):
Sharing a sentence is not in itself a finding about the gene and the disease.
tumor (41 papers, 2008 to 2026). "Even in tumor foci where ADIPOQ was drastically depressed more than 100-fold, ADIPOQ was increased 11-fold by FGFR4 deficiency." (PMID 24279986, 2013). "These included amplification of a cluster of MMPs on chromosome 11q22.3, including MMP1 and MMP3, which have been previously associated with tumour-induced muscle loss in drosophila models 32, as well as amplifications involving ADIPOQ (Adiponectin) on chromosome 3q27.1." (PMID 37045997, 2023). "The significant inverse associations of ADIPOQ IHC expression observed with larger tumor size and unfavorable Ki67 status also support this hypothesis." (PMID 32046756, 2020). "Additionally, the association of lower ADIPOQ IHC expression with unfavorable Ki67 status was slightly stronger, while the association of ADIPOQ IHC expression with increasing tumor size was attenuated among Black women." (PMID 32046756, 2020). "ADIPOQ levels have been associated with the activation of apoptotic enzymes in the caspase cascade, which led to cell death, modulation of the expression of several apoptosis-related genes in myelomonocytic cells, and reduction of tumor neovascularization." (PMID 22087284, 2011). "Immunofluorescence staining of Panc02‐shCont tumor tissues with anti‐AdipoQ antibody revealed the presence of AdipoQ+ cells, which also exhibited positive staining for GLUT4, an adipocyte marker protein." (PMID 40751595, 2025). "Key characteristics of sST2‐knockdown subcutaneous tumors observed were increased tumor angiogenesis, reduced AdipoQ expression, NF‐κB activation, and N2 TAN accumulation." (PMID 40751595, 2025). "Specifically, women diagnosed at a younger age had significantly higher methylation level of ADIPOQ in the tumor tissue compared to older patients (53 vs. 62 years, p = 0.037)." (PMID 41226688, 2025). "To confirm the gene expression data, we probed NPE and PE tumor sections with adiponectin the product of the AdipoQ gene that was highly upregulated in the NPE tumors and compared its expression pattern with that in human RMS TMAs." (PMID 36127469, 2022). "ADIPOQ/adiponectin was the most significant down-regulated gene in tumor tissues (log2FoldChange = −13.51, adjusted P = 4.16E-23)." (PMID 32547950, 2020). "Further, orthotopic implantation of Pan02 cell line showed a significant increase in tumor volume by higher vascularization (more microvessel density) and decreased apoptosis in AdipoQ knockout mice as compared to WT animal." (PMID 30567565, 2018). "In this regard some clinical studies suggest that circulating AdipoQ inhibit tumor cell proliferation by decreasing AKT and beta catenin levels across multiple malignancies (breast, colon and prostate)." (PMID 30567565, 2018). "Overall, the findings from this study suggested AdipoQ to be a tumor suppressive role in PC by directly inhibiting proliferation and inducing apoptosis." (PMID 30567565, 2018). "Given that high methylation corresponds to low expression, the hypermethylation of ADIPOQ in younger patients may result in reduced adiponectin levels, which could promote tumor growth and metastasis." (PMID 41226688, 2025). "We found that compared with orthotopic tumor growth, subcutaneous implantation resulted in significantly increased tumor growth, accompanied by downregulation of anti‐inflammatory adiponectin (AdipoQ) expression, activation of NF‐κB, upregulation of Cxcl3 expression, and accumulation of N2 TANs." (PMID 40751595, 2025). "Since AdipoQ has been reported to enhance adipocyte lipid storage, this result may suggest a reduction of this process in BM involved by neoplasia." (PMID 35757418, 2022). "In summary, exosomal miR-9-5p could evident inhibit the expression pattern of ADIPOQ in vivo and mediate tumor cell resistance to TAM." (PMID 33451320, 2021).
tumor (continued). "In addition, knockdown of AdipoR1, the major receptor of AdipoQ in these mouse cell lines (H7 and Panc02) followed by subcutaneous injection reduced tumor weight, size, and expression of Ki-67 (proliferation marker)." (PMID 30567565, 2018). "Inhibitory role of AdipoQ in halting tumor progression has also been observed." (PMID 30567565, 2018). "This adipokine can inhibit cell proliferation and promote apoptosis, which could protect against breast carcinogenesis and progression; however, it has been suggested that ADIPOQ participates in BC growth through the presence of the estrogen receptor α (ERα) in the tumour." (PMID 41456223, 2025). "Therefore, the aberrant methylation and subsequent silencing of ADIPOQ could facilitate tumor development and therapy resistance, positioning it as a compelling candidate for investigation." (PMID 41226688, 2025). "Manieri’s research shows that AdipoQ can activate two proteins in hepatocytes, p38α and AMP-activated protein kinase, which can prevent cell proliferation and damage tumor growth." (PMID 33256658, 2020). "For instance, up-regulation of ADIPOQ, AGTR1, AHNAK, ENDRA, RBP7 and SLIT2 was correlated with larger tumour size and more advanced tumour stage." (PMID 33184436, 2020). "Tumor status induced a significant decrease in the expression of FIGF (P < 0.0001), ADIPOQ (P < 0.0001), LEP (P = 0.0009), PTHLH (P = 0.0345) and FOS-like Antigen 1 (FOSL1; P < 0.0001) compared with expression in corresponding non-tumor tissue." (PMID 27857161, 2016). "Besides, we identified two genes, ADIPOQ and CTH, that exhibit a mixed pattern across tumor stages and ER/PR status." (PMID 40420636, 2026). "LEP, ADIPOQ, and OXTR manifest lower expression in tumor samples." (PMID 27857161, 2016). "A negative correlation has been also demonstrated between ADIPOQ levels and tumor size and grade." (PMID 33182810, 2020). "Moreover, ADIPOQ is a potent inhibitor of the PI3K-mTOR pathway, either through phosphorylation of the protein raptor, a component of mTOR complex 1 (mTORC1), or by regulating the activity of tuberin (TSC2), which is a tumour suppressor." (PMID 30883598, 2019).
metabolic disorders (27 papers, 2009 to 2025). "This narrative review summarizes current knowledge on the role of adiponectin and ADIPOQ gene variants in metabolic disorders, providing a foundation for future research and potential clinical applications." (PMID 40565591, 2025). "Adiponectin is encoded by the ADIPOQ gene and participates in the pathogenesis of cardiovascular and metabolic diseases." (PMID 31561637, 2019). "Another factor implicated in metabolic diseases is adiponectin (ADIPOQ), representing the most abundant adipocyte-derived protein." (PMID 21286314, 2010). "Thus, the results indicate that minor A allele of rs182052 of the ADIPOQ gene is significantly associated with a decrease in serum adiponectin levels, and two SNPs (rs182052 and rs266729) of the ADIPOQ gene are significantly associated with cardiovascular and metabolic diseases." (PMID 31561637, 2019). "Severe hypothermia causes metabolic disorders in cerebral cortex nerve cells, significantly altering ferroptosis-related genes such as PPARG, SCD, ADIPOQ, SAT1, EGR1, and HMOX1." (PMID 39125656, 2024). "The relationship between different genetic variants and BMI in KOA patients has been shown, among which there are a large number of genes associated with metabolic disorders (FTO, ADIPOQ, LEP, SREBP2) and other genes (GDF5, TGFB1, etc.)." (PMID 38424630, 2024). "Consistently with these findings, and in line with hesperidin’s beneficial effect on metabolic disorders and its anti-inflammatory properties, we detected increased ADIPOQ expression in the breast muscle in the E1 treatment group." (PMID 33807218, 2021). "For example, the ADIPOQ, AMY1A, CFB, HP and HBB are associated with the metabolic diseases, while the FBP4, HP, LPL and MYL2 are related to the cardiovascular diseases." (PMID 24204599, 2013). "For example, a study demonstrated that remodeling of the ECM in adipose and muscle tissue plays a pivotal role in metabolic disease development, identifying genes such as TCF7L2, ADIPOQ, CD36, PPARG, IL6, SIRT1, and COL5A1 as key regulators of inflammation." (PMID 41303617, 2025). "Leptin (gene: LEP), adiponectin (gene: ADIPOQ), and resistin (gene: RETN) are candidate adipokines for investigation of metabolic diseases, as all three are involved in regulation of metabolism, appetite, and insulin sensitivity." (PMID 28413567, 2017). "Adiponectin (also known as Acrp30, AdipoQ and GBP28), an adipocytokine secreted by adipocytes, has been receiving a great deal of attention due to its insulin-sensitizing effects and possible therapeutic use for metabolic disorders." (PMID 26468982, 2015). "Adiponectin (also known as Acrp30, AdipoQ, and GBP28), an adiocytokine secreted by adipocytes, has been the recent focus of intense research because of its insulin-sensitizing effect and possible therapeutic target for metabolic disorders." (PMID 25099270, 2014). "In individuals with IGT and T2DM, circulating CTRP7 levels showed an opposite trend to circulating ADIPOQ levels; thus, the increase in CTRP7 levels may represent a compensatory response to decreased ADIPOQ levels or the stimulation of IR and metabolic disorder." (PMID 35368863, 2022).
cardiovascular disease (23 papers, 2008 to 2025). "Polymorphisms in the ADIPOQ gene, which encodes the adiponectin hormone, are believed to influence cardiovascular disease risk." (PMID 41059404, 2025). "Our study revealed significant association of AdipoQ (rs1501299) gene polymorphism and oxidative stress with cardiovascular disease in Punjabi women of North West India." (PMID 33584140, 2021). "The variants of AdipoQ gene were found to be associated with obesity, metabolic syndrome markers and cardiovascular disease." (PMID 33584140, 2021). "The effects of two common single nucleotide polymorphisms (SNPs) of ADIPOQ gene, T/G substitution in exon 2 (+45T/G) and G/T substitution in intron 2 (+276G/T), on cardiovascular disease have been investigated in Caucasian and Korean populations." (PMID 26781170, 2016). "A recent meta-analysis also showed that the associations between rs266729 in the ADIPOQ and cardiovascular disease were significant." (PMID 23590551, 2013). "These loci included one on chromosome 3, which harbours the ADIPOQ gene, an attractive candidate for predisposing individuals to cardiovascular disease." (PMID 24330659, 2013). "Variations in AdipoQ gene can protect against CHD (as with rs2082940T) or associated with CHD risk (as with rs3774261G) in Northeast Han Chinese – findings that will help shed light on the reported conflicting roles of AdipoQ in cardiovascular diseases." (PMID 26754433, 2016). "The genes encoding human fetuin-A (AHSG) and human adiponectin (ADIPOQ), which is almost exclusively secreted from adipose tissue and represents an important determinant of whole-body insulin sensitivity and cardiovascular disease, are located next to each other on chromosome 3q27." (PMID 18335040, 2008). "Recently, a meta-analysis study suggested that the SNP +276G/T of ADIPOQ gene is a low risk factor for development of cardiovascular disease in T2DM; however, the association of this polymorphism with the susceptibility to cardiovascular disease in other populations remains unknown." (PMID 26781170, 2016). "Proteins associated with lipid metabolism and cardiovascular health were also reduced, including ADIPOQ (also known as APM1, associated with cardiovascular disease) and IGFBP3 (a marker reflective of renal impairment)." (PMID 41301692, 2025). "Measurement of adiponectin levels in blood and its association with markers of oxidative stress can throw more light on the role of AdipoQ (rs1501299) gene in the occurrence of cardiovascular disease." (PMID 33584140, 2021). "Inconsistencies have existed in research findings on the association between cardiovascular disease (CVD) and single nucleotide polymorphisms (SNPs) of ADIPOQ, triggering this up-to-date meta-analysis." (PMID 29807528, 2018). "The genes ADIPOQ, ACE2, APOE and CETP are implicated in these processes and polymorphism in these genes have been reported responsible to cause cardiovascular diseases (CVD) in diabetic patients." (PMID 28761062, 2017). "Polymorphisms in adiponectin-related genes (ADIPOQ, ADIPOR1, ADIPOR2) have been examined for relationships with obesity, insulin resistance and diabetes, cardiovascular disease, and to circulating adipokine levels, but many gaps in knowledge remain." (PMID 24586568, 2014). "Only a few previous studies have explored the association of AdipoQ (rs1501299) polymorphism and the concomitant presence of cardiovascular disease with nearly no reports from Northern Punjabi population of India particularly in women at menopausal age." (PMID 33584140, 2021). "Findings from previous studies on these AdipoQ gene polymorphisms in relation to CHD and other cardiovascular disease risks are not only inconsistent and inconclusive, but most of these studies are conducted on animal models, Europeans or other Western populations." (PMID 26754433, 2016).
infection (4 papers, 2019 to 2025). The state of being infected such as from the introduction of a foreign agent such as serum, vaccine, antigenic substance or organism. "Several differentially expressed genes identified in our study (i.e., ADIPOQ, CCL3) are related to tumor necrosis factor (TNF), a cytokine that produces an immune response to help prevent the spread of infection." (PMID 31788200, 2019). "Transcript levels of ADIPOQ remained unchanged as compared to mock-infected cells in any condition, suggesting that infection did not significantly alter adipocyte function at these time points." (PMID 41157583, 2025).
degenerative diseases (1 paper, 2025). "IF regulates lipid metabolism primarily via genes including FABP4, WNT10B, PCK1, PLIN1, LEPR, and ADIPOQ, providing energy for cold adaptation, whereas PF positively influences in vivo degenerative diseases mainly through genes such as ATP5F1A, ATP5PO, SDHB, NDUFS8, SDHA, and COX5A." (PMID 40136641, 2025).
infectious disease (1 paper, 2020). A disorder directly resulting from the presence and activity of a microbial, viral, or parasitic agent in humans. "However, very few studies have investigated ADIPOQ haplotypes in the context of infectious diseases." (PMID 33897209, 2020).
ADIPOQ also shares sentences with these, for which no sentence is quoted: metabolic dysfunction-associated steatotic liver disease (5 papers); hepatocellular carcinoma (4); lung carcinoma (4); ovarian carcinoma (4); hypertriglyceridemia (3); inflammatory bowel disease (3); type 1 diabetes mellitus (3); acute myocardial infarction (2); fatty liver disease (2); heart disease (2); osteosarcoma (2); scoliosis (2); abdominal aortic aneurysm (1); acute leukemia (1); adenocarcinoma (1); adolescent idiopathic scoliosis (1); alcoholic fatty liver disease (1); alcoholic liver diseases (1); anaplastic thyroid carcinoma (1); anorexia nervosa (1); aortic valve disease (1); aortic valve stenosis (1); arteriosclerosis (1); Arthritis (1); Ascites (1); bladder cancer (1); Bovine mastitis (1); Cachexia (1); cerebrovascular disease (1); chronic heart failure (1).
A further 52 diseases each share a sentence with ADIPOQ in 1 paper.